FSHB (follicle stimulating hormone subunit beta)
Diseases named in the same sentence as FSHB in open-access papers (continued):
Sharing a sentence is not in itself a finding about the gene and the disease.
tumor (12 papers, 2010 to 2025). "A novel variant of the lytic peptide phor, composed of 18 amino acids (Phor18) conjugated to FSHβ has been shown to inhibit the growth of PC-3 xenografts by targeting FSHR-expressing cancer or endothelial cells of tumor vessels." (PMID 40490708, 2025). "FSHβ 33–53 and FSHβ 81–95 peptides promote paclitaxel-loaded NP entry into the FSH receptor (FSHR)-positive ovarian tissue to achieve excellent anti-tumor effects." (PMID 38675151, 2024). "This seems to occur even though FSHβ and LHβ show similar staining patterns within the gonadotroph tumours, as found in the present study." (PMID 36952069, 2023). "However, 46.4% of the LHβ positive tumours and 66.7% of both FSHβ and LHβ positive tumours presented positive TGFBR3L staining (p < 0.001)." (PMID 36952069, 2023). "We have recently shown that FSHβ staining of the gonadotroph PitNETs correlated with circulating plasma FSH levels, suggesting that some of the FSH produced by the tumours enters the circulation." (PMID 36952069, 2023). "In order to achieve both efficient tumor retention and rapid RES clearance, the interval between two injections of DCNPs-L1-FSHβ (first) and complementary nanoprobes DCNPs-L2 -FSHβ (second) was optimized." (PMID 30042434, 2018). "The fourth cluster of non-PIT-1 tumor cells was predominantly composed of SF-1 lineage cells with overexpression of follicle stimulating hormone subunit beta (FSHB)." (PMID 40959438, 2025). "When investigating the different subgroups of gonadotroph tumours we found that none of the tumours staining for FSHβ alone (n = 6) and only one of the tumours not staining for neither FSHβ nor LHβ (n = 12) presented positive for TGFBR3L." (PMID 36952069, 2023). "The hormone negative but SF1 positive gonadotroph tumours were more often TGFBR3L negative than tumours staining for LHβ alone or both FSHβ and LHβ." (PMID 36952069, 2023). "Several single nucleotide polymorphism (SNPs) have been associated with the disease, for example in the region of the wingless-type mammalian mouse tumor integration site family member 4 (WNT4), vezatin (VEZT) and follicle stimulating hormone beta polypeptide (FSHB)." (PMID 34544404, 2021). "The tumor cells showed positive expression of FSHβ, while LHβ was mostly negative." (PMID 38421932, 2024). "The FRET-specific fluorescence for both tumor and harvest organs of the complementary group were more than twice as high as the noncomplementary group (DCNPs-L1(Cy5)-FSHβ + DCNPs-L1(Cy7)-FSHβ), demonstrating the colocalization assembly of the two complementary components can occur within tumors." (PMID 30042434, 2018). "Also, no tumours exclusively staining for FSHβ, and not LHβ, presented TGFBR3L staining." (PMID 36952069, 2023). "Of the gonadotroph tumours twelve did not stain (IRS 0) for neither FSHβ nor LHβ, six stained only FSHβ, 28 stained for LHβ alone and 70 for both FSHβ and LHβ." (PMID 36952069, 2023). "TGFBR3L was associated to IRS of LHβ (median 2 [IQR 0–3] in TGFBR3L negative and median 6 [IQR 3–9] in TGFBR3L positive tumours, p < 0.001), but not to the IRS of FSHβ (p = 0.32)." (PMID 36952069, 2023). "TGFBR3L staining was present in 52% (n = 60) of the gonadotroph tumours, and in one double-PitNET (positive for FSHβ and SF-1 in some cells, and for ACTH and T-Pit in others), while all other tumours were negative." (PMID 36952069, 2023). "We found that the groups staining for either FSHβ, LHβ or both more often presented staining for TGFBR3L than tumours not staining for the gonadotropins." (PMID 36952069, 2023).
cancer (1 paper, 2025). A tumor composed of atypical neoplastic, often pleomorphic cells that invade other tissues. "The fusion lytic peptide Phor 21 conjugated with the FSHβ chain 33–53 fragment (Phor21-FSHβ33-53 C/S) specifically targeted and destroyed cancer cells expressing FSHR." (PMID 40490708, 2025).
metabolic disease (1 paper, 2017). A congenital disorder (due to inherited enzyme abnormality) or acquired (due to failure of a metabolically important organ) disorder resulting from an abnormal metabolic process. "The expression pattern at rs11031005 (FSHβ locus) in fat predicted a relationship to endocrine function and the pattern for rs2178575 (ERBB4 locus) in skin predicted a relationship to metabolic disease." (PMID 28068351, 2017).
FSHB also shares sentences with these, for which no sentence is quoted: female infertility (2 papers); migraine (2); uterine fibroids (2); adenoma (1); age (1); aniridia (1); anovulation (1); benign tumors (1); Central hypothyroidism (1); congenital generalized lipodystrophy (1); congenital hypogonadotropic hypogonadism (1); Frasier syndrome (1); gonadotroph adenoma (1); gynecological diseases (1); Kallmann syndrome (1); lactotroph adenoma (1); Macroorchidism (1); Menorrhagia (1); Noonan syndrome (1); oligospermia (1); Ovarian cyst (1); ovarian tumor (1); premature ovarian failure (1); Primary amenorrhea (1); somatotroph adenoma (1); uterine diseases (1); Uterine leiomyoma (1); WAGR syndrome (1).